HES1 (hes family bHLH transcription factor 1)
Diseases named in the same sentence as HES1 in open-access papers (continued):
Sharing a sentence is not in itself a finding about the gene and the disease.
tumor (continued). "Notch signaling involves receptor-ligand interactions that trigger proteolytic cleavage of Notch receptors, promoting the nuclear translocation of the notch intracellular domain (NICD) to regulate gene transcription, including hairy and enhancer of split-1 (HES1) linked to tumor progression." (PMID 41488655, 2025). "Ptf1a + /Cre-mediated Hes1 deletion caused defective exocrine differentiation with accumulation of acinar progenitors, which may contribute to the accelerated tumor development." (PMID 39548190, 2025). "We further investigated the effect of Hes1-deficiency on T cells, which can eliminate tumor cells." (PMID 39702544, 2024). "Driven by theses insights, we aimed to elucidate the molecular mechanism by which Notch signaling in TAMs regulates tumor growth and how HES1 deficiency alters the TME into an immunostimulatory state to assess the potential of HES1 targeting for novel cancer immunotherapy strategies." (PMID 39702544, 2024). "We identified a pivotal role for the Notch signaling pathway in shaping TAM function, suggesting that T-cell dysfunction in the TME is caused when the Notch target, HES1, in TAMs is upregulated by tumor-associated factors (TAFs), which, in turn, increases the expression of arginase-1." (PMID 39702544, 2024). "Elevated expression of Notch1 and Hes1 in HCC tissues is associated with malignant characteristics of the tumor, indicating a poor prognosis for patients, whereas reduced expression of PTEN may promote the occurrence and progression of HCC." (PMID 39537605, 2024). "Also at the protein levels, the cleaved, active form of Notch1 (NICD1) and Hes1, which is encoded by a Notch target gene, were decreased in Ap4-deficient tumor organoids indicating a decrease in Notch signaling." (PMID 30177706, 2018). "Consistent with this reduction in NOTCH levels, significant decreases in NOTCH target genes (Deltex1, Hey1, and Hes1) are also observed in tumor-associated T-cells, suggesting that tumor-associated T-cells have repressed NOTCH signaling and potentially decreased effector function." (PMID 30967879, 2018). "HES-1 gene is an important effector of the Notch pathway that has been implicated in regulating the proliferation, differentiation and apoptosis in multiple tumor cell types." (PMID 23711233, 2013). "Expression of HES1 mRNA is frequently utilized as an indicator of Notch activity and Notch/HES1 activation has been implicated in a variety of human cancers with oncogenic activity in some tumor types and tumor suppressor activity in others." (PMID 23816051, 2013). "In addition, this anti-tumor effect may be associated with a reduction in key factors that promote tumor development such as Notch-1, Hes-1, VEGF, and MMPs." (PMID 39183411, 2024). "Therefore, induced HES1-loss in vitro promoted tumor invasion and EMT." (PMID 37749297, 2023). "However, IL10 increase in HES1 (−) tumors may implicate the complex tumor microenvironment remodeled by KRAS mutation and/or HES1-loss." (PMID 37749297, 2023). "Therefore, HES1 likely functions as a migration-proliferation dichotomy node that controls tumor invasion and proliferation in KRAS mutant CRC, and its loss may be a predictor of tumor invasion and metastasis." (PMID 37749297, 2023). "In contrast, Hes1, a Notch target gene normally associated with stemness and absorptive cell differentiation, and Phlda2, a growth restriction gene in development and a tumor suppressor, were upregulated in APC and AOM/DSS tumor cells, but not in squamous cells." (PMID 35600339, 2022). "In tumor tissues, the expression levels of Notch1 and Hes1 were dramatically upregulated in the IL-6 group." (PMID 41602823, 2026). "The Notch downstream target Hes1 was shown to restrict tumor development in a PDAC model with oncogenic Kras activated in the pancreas starting from embryonic stage." (PMID 39548190, 2025). "The Notch-Hes1 pathway promotes the generation of MDSCs/Tregs, thereby suppressing anti-tumor immune responses." (PMID 40755759, 2025).
tumor (continued). "Considering the relevance of HES1 expression in the survival of tumor cells and as the main target of Notch signaling, we determined the effect of 2OHOA on the expression of this gene in U-87 MG and U-118 MG GBM cell lines." (PMID 39400678, 2025). "Future research should delve into the specific epigenetic regulatory mechanisms of Hes1 and explore its clinical translation potential, aiming to provide more effective solutions for tumor treatment." (PMID 40755759, 2025). "In the tumors treated with 2OHOA that reduced in size there was a strong positive correlation between HES1 expression and tumor volume." (PMID 39400678, 2025). "Targeting Hes1 represents a promising strategy to overcome tumor recurrence and drug resistance, with profound clinical translational potential." (PMID 40755759, 2025). "Combined inhibition of Hes1 and Smo reverses the tumor sphere formation and increase in invasive cell populations caused by miR-7-5p suppression, highlighting the synergistic role of Notch and Hedgehog pathways in GCSC invasion." (PMID 40755759, 2025). "In vivo studies demonstrate that Hes1 knockdown reduces breast CSC-derived tumor size and weight, confirming its role in tumor growth inhibition." (PMID 40755759, 2025). "HES1, a downstream effector and surrogate marker for active Notch, was not only present in the nucleus but also in the cytoplasm in some of the tumor cells." (PMID 40387567, 2025). "Herein, we selected two representative Notch receptors (NOTCH1 and NOTCH2), NICD (NOTCH1 intracellular domain, also known as activated NOTCH1), and HES1 (downstream effector) as targets and conducted an immunohistochemical study on tumor samples." (PMID 40387567, 2025). "A genomic analysis of the Notch pathway in 16 glioma tumor-initiating cell populations identified genes such as NOTCH1, NOTCH3, MAML1, JAG2, HES1, and DLL-3, which were associated with active Notch signaling and enriched in tumors responsive to treatment." (PMID 40003637, 2025). "Single-cell RNA sequencing analysis further revealed that NOTCH signaling components, such as GALNT11, HES1, KIT, and SLC35C1, are significantly upregulated in tumor-associated monocytes/macrophages." (PMID 40361382, 2025). "Conversely, the methylation of miRNA-9 leads to its downregulation, promoting Hes1 expression and subsequently enhancing tumor cell proliferation and differentiation." (PMID 40755759, 2025). "Conversely, Hes1 downregulation suppresses spheroid formation, cell invasion, tumor proliferation/migration, and triggers apoptosis." (PMID 40755759, 2025). "Hes1 plays a crucial role in tumor immune escape by influencing immunosuppressive cells and immune checkpoint molecules within the TME." (PMID 40755759, 2025). "Conditional knockout of Hes1 in TAMs enhances the infiltration and activation of cytotoxic T cells, significantly inhibiting tumor growth." (PMID 40755759, 2025). "Notch-related signals activate HES1 through DLL1-Notch1/2-mediated ligand-receptor binding between tumor cells, further regulating the expression of differentiation-inhibitory genes." (PMID 40989695, 2025). "We isolated CD11b+Gr1+ neutrophils, CD11b+F4/80+Gr1− macrophages, and CD11b+CD11c+ DCs, CD3+ T cells, B220+ B cells from tumor-bearing mice and measured their Hes1 expression using qRT-PCR." (PMID 39702544, 2024). "Consistent with other findings, Hes1-cKO slowed TC-1 tumor growth; however, depletion of CD4+ T cells completely abolished this effect." (PMID 39702544, 2024). "Given that MDSCs are also known to function similarly to TAMs, we examined HES1 protein expression in both TAMs and MDSCs from tumor, spleen, and bone marrow of TC-1 tumor bearing mice." (PMID 39702544, 2024). "Based on these findings, it can be inferred that Hes1-cKO and PD-1 blocking antibody contributes to a slower progression of tumor growth." (PMID 39702544, 2024).
tumor (continued). "To assess the effect of tumor-derived soluble factors on macrophage activation and induction of HES1 expression, we used transwell co-culture experiments." (PMID 39702544, 2024). "Type-2 conventional DCs, which have macrophage-like characteristics and express CD11b, are recruited to tumor tissues; therefore, it is likely that Hes1 expression is decreased in intratumoral DCs." (PMID 39702544, 2024). "As tumor conditioned media contain a number of tumor-promoting cytokines and growth factors that suppress immune responses, we investigated Hes1 expression in response to these stimuli." (PMID 39702544, 2024). "Administration of anti-PD-1 monoclonal antibody inhibited tumor growth to a greater extent in Hes1-conditional KO mice than in WT mice." (PMID 39702544, 2024). "To examine the impact of conditional KO of Hes1 in TAMs on anti-tumor immunity, we analyzed infiltrating immune cells in subcutaneous TC-1 tumor tissues using immunohistochemistry and flow cytometry." (PMID 39702544, 2024). "To understand how HES1 expression in macrophages is activated in response to tumor-promoting conditions, we knocked down Rbpj using siRNA, followed by treatment with mouse tumor cell conditioned medium (CM)." (PMID 39702544, 2024). "Taken together, these data imply that Hes1 on TAMs promotes tumor growth in a way that limits the activities of CD4+ and CD8+ T cells and represents a promising therapeutic approach, especially when combined with existing anti-tumor therapies." (PMID 39702544, 2024). "We observed a significant increase in HES1 expression, in parallel with that of pro-tumor macrophage markers, including ARG1, CD206, PD-L1, and Notch signaling-related proteins." (PMID 39702544, 2024). "Our study showed that expression levels of Notch target Hes1 were increase in TAMs and mice with conditional knockout of Hes1 gene in TAMs exhibited decreased tumor growth, with increased infiltration and activation of cytotoxic T cells in tumors." (PMID 39702544, 2024). "ASCL1 inversely correlates with YAP1 signaling, and in GEMMs of SCLC, expression of constitutively active Yap1 resulted in tumor phenotype switching by upregulation of Notch2 and downstream Rest and Hes1." (PMID 39456533, 2024). "We observed a notable decrease in tumor growth, both in volume and weight, in Hes1-cKO with PD-1 blockade when compared to WT with PD-1 blockade." (PMID 39702544, 2024). "On treatment with tumor-CM, enhanced luciferase activity was seen for the promoter sequence of Hes1 with the RBPJ consensus binding motif." (PMID 39702544, 2024). "As expected, conditional KO of Hes1 reduced pro-tumor gene expression and promoted anti-tumor gene expression." (PMID 39702544, 2024). "ARG1 was upregulated by tumor-CM, whereas HES1 knockdown by siRNA resulted in reduced ARG1 expression." (PMID 39702544, 2024). "Similar outcomes were observed in a THP-1 cell line, transfected with siRNA targeting HES1 and treated with tumor conditioned media (CM) produced by AGS cells." (PMID 39702544, 2024). "Conditional knockout of Hes1 in TAMs significantly enhanced tumor infiltration and activation of cytotoxic T cells, leading to reduced tumor growth." (PMID 39702544, 2024). "Although tumor cells harboring Rest and Hes1 upregulation were slower-growing, they were more resistant to treatment with cisplatin and etoposide and acted as part of the TME in providing trophic support to other tumor cells." (PMID 39456533, 2024). "To examine the synergistic anti-tumor effects of Hes1-cKO and an PD-1 immune checkpoint blockade, we utilized two subcutaneous animal tumor models (TC-1 and MC-38) and administered PD-1 blocking antibody (RMP1-14) by intraperitoneal injection." (PMID 39702544, 2024). "Expression of tumor promoting factors was critically altered in Hes1-conditional KO TAMs, leading to the improved tumor microenvironment." (PMID 39702544, 2024).
tumor (continued). "The growth of Jag2OE tumor cells in co-culture was markedly diminished by Hes1 knockdown in mesothelial cells." (PMID 38575576, 2024). "We also injected mice with murine breast (EO771), colon (MC-38), or lung (TC-1) tumor cells and found that Hes1 deletion resulted in reduced tumor growth in all three models." (PMID 39702544, 2024). "We also confirmed that HES1 levels were regulated in an RBPJ-dependent manner on treatment with tumor conditioned media from B16F10 or TC-1." (PMID 39702544, 2024). "HES1 expression was upregulated by IL-4, EGF, TGF-β, and other factors, consistent with earlier reports, including studies showing that tumor-CM contain Hes1-inducing factors." (PMID 39702544, 2024). "We also confirmed that the expression of HES1 increases concurrently with tumor development using MMTV-PyMT mice." (PMID 39702544, 2024). "HES1 expression was also examined in macrophages differentiated from bone marrow and spleen, as well as TAMs sorted from tumors of TC-1 tumor-bearing mice." (PMID 39702544, 2024). "Taken together, HES1 expression increased only when a tumor promoting stimulus was applied, and ARG1 expression also increased under the same circumstances." (PMID 39702544, 2024). "For example, tumor cells rely on HES1 for self-renewal, stemness, proliferation, epithelial–mesenchymal transition, and resistance to therapy." (PMID 39702544, 2024). "Taken together, it is likely that HES1 plays an oncogenic role in ccRCC development by directly targeting miR-138–2, and miR-138–2 acts as a tumor-suppressor in ccRCC development through the direct targeting of the oncogenic NOTCH signaling pathway." (PMID 36973704, 2023). "Our work revealed that loss of HES1 expression positively correlated with matrix remodeling and epithelial-mesenchymal transition (EMT) but negatively correlated with tumor cell proliferation." (PMID 37749297, 2023). "We found that tumor cells in 36.4% (4/11) cases of HES1 (−) group were positive for phospho-STAT3 while only 9.1% (1/11) of HES1 (+) cases were positive for phospho-STAT3 but statistical significance was not reached." (PMID 37749297, 2023). "Our findings identify signaling pathways and cytokines impacted by HES1 that are responsible for promoting tumor progression in KRAS mutant CRCs." (PMID 37749297, 2023). "Our results also suggest that alteration of HES1 expression in tumor cells can rewire the tumor microenvironment and affect tumor progression through M2 macrophage polarization." (PMID 37749297, 2023). "In contrast, it is known that HES1 mediates the tumor-suppressive roles of NOTCH1 signaling in AML development as well, which underlines the context-dependent manner of NOTCH1 signaling." (PMID 37833915, 2023). "The significant upregulation of the NOTCH1 target gene, Hes1, significantly increased the tumor volume, the positivity rate of tumor Ki67 staining, and lung metastasis in the subcutaneous xenograft mouse model." (PMID 36975516, 2023). "Taken together, these data demonstrated that SOX1 acts as a tumor suppressor by directly inhibiting HES1 during the development of NSCLC." (PMID 37190139, 2023). "Downstream of Notch and Hedgehog signalling, HES1 contributes to preventing tumour cell differentiation by recruiting repressive histone deacetylases (HDACs) to its target genes, leading to chromatin compaction." (PMID 37608096, 2023). "In summary, our study indicates that aberrant HES1 expression correlates with tumor matrix remodeling in KRAS mutant CRC." (PMID 37749297, 2023). "We found that loss of HES1 expression positively correlated with matrix remodeling and epithelial-mesenchymal transition (EMT) but negatively correlated with tumor cell proliferation." (PMID 36824959, 2023). "Consistent with our results, a marked up-regulation of pre-miR-138–2, miR-138-5p and miR-138–2-3p was detectable in HES1-depleted tumors, and the tumor volume and weight were obviously reduced in HES1-depleted tumors." (PMID 36973704, 2023).
tumor (continued). "Corroborating the in vitro findings, the tumours from the DPC‐treated mice exhibited reduced pERK as well as lower expression of HES1 and mTOR." (PMID 37165578, 2023). "In summary, our results indicate that the direct anti-tumor effect of HDACi domatinostat is mediated, at least in part, by downregulation of HES1, leading to induction of IFNα, which in turn induces apoptosis in MCC cells." (PMID 37071208, 2023). "Overexpression of HES1-FLAG in SOX1-expressing H1299 cells partly reversed the tumor-suppressive effect of SOX1 expression compared with the control." (PMID 37190139, 2023). "To elucidate the role of Notch signaling on cell cycle reactivation in the S-cells-derived xenograft tumors, we evaluated the expression of HES1 in both mid- and end-point tumor xenografts." (PMID 36718360, 2023). "While myeloid derived suppressor cells are likely the major source of IL10 in CRC37, we found that HES1 downregulation in CRC cells increased IL10 expression suggesting a potential tumor-intrinsic role of IL10 in the pathogenesis of HES1 (−) CRCs." (PMID 37749297, 2023). "Compared with the corresponding normal adjacent tissues, the protein levels of HES1 were significantly increased in the tumor tissues." (PMID 37957183, 2023). "Our results demonstrate that the direct anti-tumor effect of HDACi domatinostat on MCC cells is at least in part mediated via decreased HES1 expression allowing the induction of IFNα, which in turn causes apoptosis." (PMID 37071208, 2023). "Although Notch signalling has been extensively studied in the regulation of embryonic and tumour vascular development, the role of the Notch transcription factors Hey1/Hes1 is not yet fully understood." (PMID 35318338, 2022). "Complementary genetic and pharmacologic approaches to block HES1 increased myogenic differentiation and impaired in vitro cell and in vivo tumor growth." (PMID 36037042, 2022). "Immunohistochemistry also showed lower expression levels of stemness markers, Notch-related, and Wnt-related genes, including HES1 and CYCLIN D1, in the SHMT2-deficient tumor groups than in the control tumor group." (PMID 36077112, 2022). "The results from qRT-PCR analysis showed that the expression of Notch2, NICD, Hes1, and Hey1 in murine tumor tissues from NEDD4L-overexpressed group was significantly decreased compared with control group." (PMID 35646490, 2022). "These gain‐ and loss‐of‐function experiments in vitro and analysis of available human tumor datasets suggest a functional relationship between HES1, YAP1, and CDKN1C in FN‐RMS, with both HES1 and YAP1 upstream of CDKN1C." (PMID 36037042, 2022). "Differential gene expression analysis, comparing LIPECs in tumor versus peri-tumoral tissues, revealed HES1 as the only significantly upregulated gene in tumor LIPECs." (PMID 36127427, 2022). "Inhibition of HES1 in vivo via conditional expression of a HES1‐directed shRNA or JI130 dosing impaired FN‐RMS tumor xenograft growth." (PMID 36037042, 2022). "The real-time PCR results confirmed that hypoxia significantly upregulated Notch1, Hes1, and Hey1 mRNA expression in tumor cells (P < 0.05)." (PMID 35982489, 2022). "Changes in NOTCH2 expression were significantly associated with tumour differentiation grade (p = 0.03) while HES1 expression—with tumour histological type (p = 0.007)." (PMID 35136410, 2022). "Similar to the genetic inhibition studies, HES1 pharmacologic inhibition by JI130 inhibited tumor xenograft growth over time, with lower average tumor weight after necropsy." (PMID 36037042, 2022). "Bulk-RNAseq and scRNAseq revealed that, in addition to NAMPT inhibition, FK866 regulates tumor metastasis, cell migration, invasion, DNA repair machinery, redox homeostasis, autophagy, as well as cancer stemness–related genes, HES1 and CD44." (PMID 36497496, 2022). "HES1, a Notch signaling pathway target, plays both oncogenic and tumor suppressor roles in different cell types." (PMID 36389757, 2022).